CD4 (CD4 molecule)
Diseases named in the same sentence as CD4 in open-access papers (continued):
Sharing a sentence is not in itself a finding about the gene and the disease.
infection (continued). "Residual viremia was not correlated with the level of infection in PBMC by droplet digital PCR (rho = −0.25, P = 0.18), the level of infection of CD4+ T cells in the rectal biopsies (rho = 0.12, P = 0.61), or the level of 2LTR circles (rho = −0.109, P = 0.57)." (PMID 23459007, 2013). "Although extremely rare in natural infection in vivo, several pathways have been described by which HIV and SIV can adapt to use CCR5 in the presence of little-to-no CD4." (PMID 24219995, 2013). "Apoptosis of CD4+ and CD8+ T cells after infection was not affected by the administration of fibroblasts." (PMID 22815907, 2012). "We also establish that within a population of activated CD4+ T cells, HIV-1 has no detectable effect on the transcriptome of uninfected bystander cells at early time points following infection." (PMID 22876188, 2012). "No significant increase of the number of CD4+ and CD8+ T lymphocytes and dendritic cells was observed in the animals in any day after infection when compared to the uninfected animal." (PMID 22666132, 2012). "Throughout the acute phase of infection, BAFF levels correlated with plasma viral load (p < 0.0001) and inversely with circulating CD4+ T-cell counts (rho = −0.596, p < 0.0001) but not with plasma IgA (data not shown)." (PMID 22632376, 2012). "B lymphocytes, CD4−CD8−, as well as CD4+CD8− T lymphocytes were not permissive to NiV, and expansion of the CD4+CD8− cells early post infection was consistent with functional humoral response to NiV infection observed in swine." (PMID 22303463, 2012). "Using flow cytometry we showed that 4 days post infection (DPI), counts of CD4 and B-lymphocytes did not change, CD8 and γδ T-lymphocytes decreased and macrophages and heterophils increased in the spleen." (PMID 22384225, 2012). "Although pre-infection NKT frequencies did not correlate with peak or set-point viremia, there was a positive correlation with CD4+ T cell counts at 24 weeks post SIV infection, either expressed as absolute counts or as percent of baseline levels." (PMID 23028326, 2012). "CD4 T cell mediated protection in the absence of CD8 T cells and B cells has also been described in animal models of infection by VZV and in infections by other virus families, including influenza, poliovirus and West Nile virus." (PMID 23012630, 2012). "Adaptive type 1 regulatory (Tr1) CD4+ cells, which do not express CD25, FoxP3 or CD127 on their surface, have recently been identified as the main source of IL-10 in experimental murine infection with P. yoelii." (PMID 22973442, 2012). "Mice lacking MHC II or CD4 produce smaller amounts of IFN-γ (and, consequently, also of IL-12) in the early phase of the infection, but the concentration of this cytokine reaches normal levels after three weeks, due to compensation by CD8+ T cells." (PMID 22811737, 2012). "Our major findings in the blood demonstrate that there was a decrease in CD4+ and CD8+ T cells on day 7 after infection in BT-infected animals (data not shown)." (PMID 22412949, 2012). "If Foxp4 regulates CD4 T cell help, we would expect more impaired CD8 responses at later points post-infection, leading to uncontrolled infection and increased mortality, which was not evident in our shorter infection." (PMID 22912696, 2012). "The HERV-W pseudotyped particles were infectious for CD4-negative cells, suggesting a mechanism by which HIV-1 can expand its cellular tropism during natural infection." (PMID 22248111, 2012). "We identified untreated HIV-infected individuals showing non-cytopathic replication (VL>10,000 copies/mL and CD4 T-cell decay<50 cells/μL/year, Viremic Non Progressors, VNP) or rapid progression (CD4 T-cells<350 cells/μL within three years post-infection, RP)." (PMID 22312424, 2012).
infection (continued). "In our study, although no increase of CD4+ and CD8+ T cells count was observed, a significant increase of IFNγ, with peak on day 10 after infection, was observed infecting the animals with DENV-1 strain Mochizuki with a lower viral dose (7.2 × 107 PFU)." (PMID 22666132, 2012). "Although the number increases due to infection, developmental exposure to BPA did not alter the number of CD4+ T cells, including those phenotypically defined as regulatory T cells (CD3+CD4+CD25+FoxP3+) in the MLN or lung on days 7 or 9 p.i.." (PMID 22675563, 2012). "The 8 patients reaching levels of HCMV-specific CD4+ and CD8+ T-cells below the threshold chosen for immune-compromised patients were able to control the infection without antiviral treatment." (PMID 22848556, 2012). "Since T-cells have important roles in the control of Chlamydia, we then investigated the impact of the absence of TLR2 on adaptive CD4+ and CD8+ T-cell infiltration and activation during the later stages of infection (7 and 14 dpi)." (PMID 22724018, 2012). "Then, naïve CD4+CD25−splenic T cells from uninfected mice were stimulated by irradiated APCs plus anti-CD3 antibodies in the presence or absence of CD4+CD25+ T cells isolated from the lungsof B10.A and A/J mice at weeks 2 and 10 after infection." (PMID 23226464, 2012). "A recent human experimental study demonstrated that conserved and common epitope-specific pre-existing CD4+ T cell immunity, but not CD8+, plays a critical role in limiting viral shedding and severity of infection in the absence of antibody titers." (PMID 23192104, 2012). "Therefore, the viral immunological correlates of infection should be detected by multiparametric analyses (antibody, CD4+, CD8+ responses...) rather than individual analysis that may underestimate the multiple immunological variables related to infection outcome." (PMID 22737070, 2012). "Few patients were in very advanced stage of infection (none in WHO stage 4 and only 9% with CD4 count below 100 cells/mm3)." (PMID 22606289, 2012). "We have previously found that co-transfer of immune CD4+ and CD8+ T cells, but not individual transfer of either lymphocyte subpopulations, was protective in lethal infection with JEV." (PMID 23028638, 2012). "While the proportions of CD4+ and CD8+ αβ T-cells do not alter upon infection, the proportions of DN αβ T-cells are higher in TB-infected patients than in healthy donors." (PMID 23239994, 2012). "Four out of the five donors tested showed proliferation of memory CD4+ T-cells following priming with HCMV, suggesting a previous infection (data not shown)." (PMID 22870231, 2012). "In vitro HIVcs204 infection did not alter CD127 expression on immature thymic subsets (i.e. TN, ISP4 and DP subsets; data not shown) or on the more mature single positive CD4+ (SP4) or single positive CD8+ (SP8) thymocytes." (PMID 21920046, 2011). "Whereas the lymph nodes showed no significant increases in either CD4 or CD8 T cells compared to lymph nodes from non-infected mice, CD19+ B cells had expanded dramatically by day 10 of infection with live B. burgdorferi." (PMID 21637808, 2011). "The neutralization resistant MM4 and MM8 viruses ranged from being highly macrophage tropic (achieving similar titres on NP-2/CD4/CCR5 cells and MDM) to being non-MDM tropic (no or minimal levels of MDM infection)." (PMID 21887353, 2011). "More than 75% of CD4+CD25+ mLN cells co-expressed FoxP3, regardless of the stage of infection confirming that the majority of CD4+CD25+ cells can be classified as CD4+FoxP3+Tregs." (PMID 21858239, 2011). "Supporting this, an independent study has shown that distinct transcriptional profiles in both CD4+ and CD8+ T cells are established early in HIV infection by comparing between early infection, chronic progressive infection, and non-progression groups." (PMID 21410942, 2011). "There were no statistical correlations between CD4 and CCR5 expression on CD1c+ mDCs and virus loads during infection." (PMID 22174949, 2011).
infection (continued). "Similar to the immune responses analyzed in the spleen, IFNγ and TNFα production by LCMV-specific CD4+ T cells was reduced or even absent in the liver of CD8-depleted mice on day 8 and 11 after infection." (PMID 21966366, 2011). "The IIIBx strain retains CD4 binding activity showing enhanced fusion activity when CD4 and CXCR4 were coexpressed on target cells for fusion assays and we cannot rule out such activity contributing to infection in the assays performed in this study." (PMID 22163292, 2011). "This differential response is strongly suggestive of a direct effect of SIV infection of CD4+ T cells rather than non-specific immune activation or bystander apoptosis, since activated CD8+ T cells are actually increased throughout infection." (PMID 22096538, 2011). "Our results reveal consistent differences between the measurements of immune activation and regulation of PB versus LN-derived CD4 and CD8 T cells, regardless of route of infection (intravenous or mucosal)." (PMID 21483689, 2011). "In contrast, the CD4-dependent HXB2 and mNDK vector (data not shown) infections were not inhibited by these inhibitors in CD4-expressing cells, and were actually increased in TE671 and HeLa cells, as previously reported." (PMID 21541353, 2011). "Unlike monocytes and CD4+ T cells, the frequency of SIV-DNA in myeloid DCs (HLA-DR+CD11+) was extremely low during the acute phase of infection (day 11, mean: 0.015±0.004; day 14, 0.015±0.008 of DCs were infected) consistent with a previous report." (PMID 21731488, 2011). "As for K173 infection, assays using CD8+ cell-depleted PBMC showed that peptide-specific responses involved both CD4+ and CD8+ T cells in “primed” and naive animals (data not shown)." (PMID 22102819, 2011). "Finally, our data agree with earlier studies suggesting that mucosal infections, unlike IV infections, may curtail increases in viral replication fitness and rate of CD4+ T cell decline, thereby preventing an increase in the rate of disease progression with passage of the virus to new hosts." (PMID 20942954, 2010). "Adoptive transfer of Bcl10-/- CD4+ T cells prior to infection partially restored worm growth, resulting in a phenotype that was intermediate between RAG-1-/- recipients of wild type CD4+ T cells and non-reconstituted RAG-1-/- mice." (PMID 20442785, 2010). "There were no discernable differences in virus load and CD4+T cell depletion between DMPA- and non DMPA-treated macaques especially during the acute phase of infection (weeks 1-4 pi)." (PMID 19891783, 2009). "The importance of CD4+ and CD8+ T cell responses is highlighted in longterm nonprogressors (LTNPs), whose ability to control infection is correlated with the presence of strong and broadly directed HIV-specific T cell responses." (PMID 19165342, 2009). "In untreated HIV-1 clade B infection, characterized by antigen persistence and high antigen load, HIV-1-specific CD4+ T cell responses tend to be weak or absent." (PMID 19352428, 2009). "In sharp contrast to the situation prevailing in human primary CD4+ T cells, up to 50% of Jurkat cells were productively infected with HIV-1 at 5 days post-infection (data not shown)." (PMID 19146679, 2009). "The decrease in SIV replication in brain has been shown in our model to be due to the effects of IFNβ produced in response to infection that reduces SIV transcription in macrophages but does not have this effect in CD4+ lymphocytes." (PMID 20019816, 2009). "We also stimulated PBMC from HIV infected individuals with SEB to determine if CD57− memory CD4+ T cells producing IFNγ and MIP-1β had lower levels of infection than those that produced IFNγ, but no MIP-1β." (PMID 19876388, 2009). "This confirms an in vitro study showing an absence of CD4, CXCR4 or CCR5 surface expression and the lack of productive infection by either R5 or X4 virus strains of epithelial cells isolated from normal prostates." (PMID 19117522, 2008).
infection (continued). "While infection is non-productive, an intracellular pool of infectious HIV-1 is harbored for up to 48 h and fully capable of trans infecting CD4+ permissive cells." (PMID 18637194, 2008). "Finally, the HIV/HCV group has significant higher ratios of CD4+ T cells to viral loads than that in HIV-1 mono-infection even at month 33 visit, which may indicate that the HIV/HCV group will be likely to progress slower than the HIV-1 mono-infection group in the future." (PMID 19098990, 2008). "Intrarectal infection with the JR-CSF stain resulted in systemic HIV infection of the mice, but the CD4+ T cell depletion was not as dramatic as that observed after intravenous infection." (PMID 18237418, 2008). "Given that the HIV-1 NL4-3 virus used for infection is CXCR4-tropic, these results indicate that signaling from the CXCR4 receptor, but not from CD4, is critical for the ability of HIV to establish latent infection of non-activated T cells." (PMID 18808680, 2008). "While primary monocyte derived macrophages (MDM) express CD4 and CCR5 and a low level of CXCR4, they support productive infection of R5 but not X4 viruses." (PMID 18036244, 2007). "The ELISpot IFN-γ assay was used to quantify antigen-specific CD4 T cells in 21 of the 22 TB patients, nine of the BCG+ without infection group, seven of the LTBI and seven of the BCG- controls." (PMID 17655752, 2007). "Partial blocking of viral entry with CD4 and CCR5 antibodies, yet low or absent productive infection, raised the possibility that these classic fusion receptors participated in viral endocytosis." (PMID 17306567, 2007). "In the in vitro infection model, the integrated HIV-1 DNA level decreased from 1,873,330 copies/107 resting CD4+ T cells without preincubation to 173,501 copies/107 resting CD4+ T cells with two-days preincubation." (PMID 17727722, 2007). "For CD4 T cells, Vβ usage was not significantly skewed by γHV68 infection; for CD8 T cells, Vβ usage was predominantly Vβ4 biased after infection." (PMID 16733540, 2006). "IRIS usually occurs in individuals with a rapidly rising CD4 T-cell count or percentage upon initiation of ART, who develop a deregulated immune response to infection with or without reactivation of opportunistic organisms." (PMID 16181494, 2005). "Finally, the involvement of additional cytokines produced by activated CD4+ T cells, such as TNF and GM-CSF, in dictating craniotomy infection outcome remains a possibility and was not examined here." (PMID 39989461, 2025). "However, the late immune competence, marked by the reconstitution of CD4+ and B cells after PTCY, correlates with a low rate of late infectious complications with no late fatalities due to infections." (PMID 39562716, 2025). "Our findings, therefore, extend the results of previous studies, supporting that HIV-related variables, namely CD4 count, HIV-VL, and ART, may not exert an influence on Omicron infection or extended viral shedding duration in older PLWH." (PMID 41268402, 2025). "However, the increase in IFN-γ+CD4+ T-cells and IFN-γ+CD8+ T-cells was not statistically significant (p > 0.05), likely because IFN-γ secretion peaks during the initial phase of infection." (PMID 41012728, 2025). "Moreover, CXCL12 blockade did not affect the development of virus-specific memory CD4+ and CD8+ T cell responses in the blood or lungs when assessed on day 30 after SARS2-N501YMA30 infection." (PMID 39773555, 2025). "Interestingly, carriers exhibited significantly lower frequencies of IFN‐γ‐expressing CD4+ and CD8+ T lymphocytes during early infection than noncarriers." (PMID 41473407, 2025). "Protection against infection induced with a single dose of the AIBP vaccine was completely abrogated after depletion of CD4 T cells or neutralization of IL-17; the CFU counts in the anti-CD4-depleted mice were similar to those in non-immunized control mice." (PMID 41214155, 2025).
infection (continued). "The decrease of memory B cells, CD69+ and CD38+T cells, as well as the increase of PD-1+, CTLA-4+ of CD4+/CD8+T cells and double negative B cells, indicate that sustained immune responses against BA.5 infection may wane more rapidly in elderly populations." (PMID 40416973, 2025). "CD4+ ALL+ cells increased at 10 dpi, but it was not statistically significant; the percentage of CD8+ ALL+ cells, however, remained unchanged during infection while a slight increase (13%) in CD4+ ALL+ cells was observed only at 10 dpi." (PMID 39253089, 2024). "In the context of the shock and kill strategy, MVC administration as an LRA would retain its antiviral efficacy that becomes evident when administered before infection, counteracting productive HIV infection in memory CD4 T cells without promoting an increase in infection levels." (PMID 38886484, 2024). "Last, we show similar control of virus replication within the upper and lower respiratory tracts on day 10 and 28 p.i. in the absence of either CD4+ or CD8+ T cells, suggesting that antibody response is not a major driver of viral control within the respiratory tract during infection." (PMID 39178263, 2024). "However, TCM CD4+ and CD8+ αβ T cells showed a decreasing trend after successive vaccine doses in subjects without a previous natural infection." (PMID 38793803, 2024). "Additionally, at 30 days post‐infection, except for a lower frequency of TIM‐3+ CD4+ T cells in the lung of OM‐TB‐TKO mice, no other significant differences in CD4+ T cell frequencies or absolute numbers were observed." (PMID 39039808, 2024). "Participants were more likely to be within HIV-1 transmission clusters if aged 25–49 years, cadre/staff/teacher, unmarried, minority, high school or below, initial CD4 counts >500 cells/μL, no STD history, homosexual partners ≥10, special survey, long-term infection and drug resistance in general." (PMID 39176274, 2024). "Interestingly, however, spike-specific CD4 and CD8 T cells only correlated in individuals with previous infection, whereas no such correlation was found in non-infected individuals." (PMID 38594497, 2024). "However, strong CD4 and CD8 T-cell responses are not sufficient to control and eradicate infection without the presence of neutralizing antibodies." (PMID 38391780, 2024). "To test this hypothesis, we knocked out CPSF5 in primary CD4+ T cells using two independent guide RNA in three independent donors and conducted HIV-1 spreading infection assays as before alongside non-targeting, CXCR4 knock-out, and CYPA knock-out controls." (PMID 39678349, 2024). "EBOV is capable of productively infecting DCs and tissue macrophages early upon infection, while HIV-1 can only productively infect macrophages, particularly tissue macrophages, and DCs do not replicate HIV-1 but can trans-infect CD4+ T cells." (PMID 38787201, 2024). "T cells in the blood, as a proportion of live cells, showed a gradual increase over the course of infection (P < 0.001), which was driven by increased proportions of CD8+ T cells (P < 0.01) with little or no change in CD4+ T cells or CD4+CD8+ double-positive cells." (PMID 38695564, 2024). "In contrast, CD4 or CD8 T cell levels towards spike from the parental strain and the Omicron-subvariants, and cytokine expression profiles were similar irrespective of prior infection." (PMID 38594497, 2024). "We found that predominance of metabolically active Ag+ CD4+,CD27+,PD-1dim CD57dim T cells and CD8dim,CD11c+ Ag+ T cells correlates with the absence of breakthrough infection and may thus confer high immune protection." (PMID 38553477, 2024). "Moreover, CTLA-4 expression levels of vaccine-induced CD4 and CD8 T cells reactive towards spike of the parental strain and the Omicron subvariants were similarly high irrespective of prior infection." (PMID 38594497, 2024).